ICOS (inducible T cell costimulator)
Diseases named in the same sentence as ICOS in open-access papers (continued):
Sharing a sentence is not in itself a finding about the gene and the disease.
tumor (continued). "Considering the percentages of the other activating receptors ICOS, OX40, and 4-1BB by CD4+ T cells and CD8+ T cells, highest proportions were found in tumor-infiltrated T cells." (PMID 41221283, 2025). "Functional validation experiments confirmed that tumor-conditioned dendritic cells upregulate ICOSL expression and promote CD8+ T-cell activation through the ICOS–ICOSL axis, as evidenced by increased CD69 and CD25 expression." (PMID 41180156, 2025). "On the one hand, ICOS promotes the activation of effector T cells, such as CD4+ T-helper cells and CD8+ cytotoxic T cells, which are essential for antitumor immunity and tumor control." (PMID 41180156, 2025). "Surprisingly, we identified a strong correlation between HLA‐DR+ MC09 and lymphoma B cells through the ICOS/ICOSL axis, suggesting a tumor‐supportive role for MC09." (PMID 41190308, 2025). "Overall, response to multiple checkpoint and myeloid blockades is driven by both CD4 and CD8 T cells, including T cells expressing TCF, ICOS, PD-1 and KI67, as well as neutrophils and MHC+ macrophages, and MHC expression by tumor cells." (PMID 40027748, 2025). "Costimulatory molecules ICOS, TNFRSF4, and TNFRSF18 are expressed on the surface of tumor-infiltrated Tregs and favor suppressive function of Tregs." (PMID 38358826, 2024). "As CD30 was already potentially activated by endogenous tumor microenvironment reshape, we decided to focus our efforts on ICOSL, and its expression, together with that of ICOS were validated by realtime PCR confirming Nanostring data." (PMID 38839891, 2024). "Analysis revealed a close relationship between the expression of CD163, Foxp3, and ICOS in CRC tissues and tumor TNM staging." (PMID 39104717, 2024). "The relationship of ICOS, M2 macrophages, and Tregs in CRC with clinical pathological characteristics and pre-surgical tumor markers (such as CEA and CA199) was explored." (PMID 39104717, 2024). "Regulatory T cells (Tregs, CD4_cluster2) with FOXP3, CTLA4, ICOS, and BATF expression were also abundant, which has been demonstrated as tumor-specific alterations in the tissue microenvironment." (PMID 39514276, 2024). "We explored the potential of spatial distributions of immune cell subtypes (CD20, CD11c, CD163, ICOS, and CD8) within the tumor microenvironment to predict NMIPUC recurrence following BCG immunotherapy." (PMID 38731992, 2024). "The abundant expression of ICOS, LAG3, OX40, PD-1, and TIM3 at the tumor margin indicates active participation of T cells in the immune response to tumor cells, which can lead to T cell depletion." (PMID 39845973, 2024). "In this study, we assessed the expression patterns and clinical significance of ICOS in patients with NSCLC from the mRNA, protein, and serological aspects, as well as their correlation with PD-L1, tumor immune infiltrating cells and prognostic significance." (PMID 38616999, 2024). "The expression of tissue biomarkers such as TIM-3, CD137, GITR, ICOS and CTLA-4 on tumor infiltrating lymphocytes (TILs) of TETs has been recently evaluated." (PMID 38966177, 2024). "We found that it was correlated with tumor immunotherapy targets BTLA, CTLA4, HAVCR2, LAG3, PDCD1, and TIGIT in HNSC; ICOS were all significantly correlated." (PMID 39483471, 2024). "As a potential key molecule for the anti-tumor effect following anti-CTLA-4 therapy, ICOS exhibited a fourfold change in expression between Cluster 1 and Cluster 2 in our study." (PMID 39623397, 2024). "Flow cytometry was performed to confirm the MS results on several critical markers of tumor immune responses including CD25 (IL2RA), CD5, CD137 (TNFRSF9), ICOS, PD1 (PDCD1), CTLA4, and CD62L (SELL)." (PMID 38242867, 2024). "Mesturini and others discovered that ICOS in the TME inhibits the differentiation of naïve T cells into Tregs through its soluble ligand form, thereby inhibiting tumor progression." (PMID 39104717, 2024).
tumor (continued). "Indeed, biomarker-driven approaches may help to identify patients likely to benefit from ICOS agonist or antagonistic therapies and suggest that ICOS agonists may be more effective in tumors with low Treg presence or when combined with treatments that deplete tumor-infiltrating Tregs." (PMID 39684559, 2024). "ICOS+ Th1-like cells play a crucial role in the antitumor effect of anti-CTLA-4 therapy, constituting the majority of tumor-specific, IFN-γ producing CD4 T cells." (PMID 38517331, 2024). "Immediately after, we investigated the protein levels of PD-L1 and ICOS in 72 patients with NSCLC, confirming their localization and quantity in tumor tissues." (PMID 38616999, 2024). "On day 9 after tumor inoculation, we observed reduced expression of CTLA-4, KLRG1 and ICOS in Il23r-KO Treg cells." (PMID 38356059, 2024). "This indicated a positive effect of ICOS in NSCLC, but a suppressive role of PD-L1 in the tumor immune microenvironment." (PMID 38616999, 2024). "Looking at B‐lymphocytes, dendritic cells, tumor‐infiltrating macrophages, neutrophils, and other immune checkpoints, such as PDL1, CTLA4, ICOS, and VISTA, would have been more informative." (PMID 37092584, 2023). "The Treg cells in the SCC16-0016 tumor dissociate expressed markers indicative of functional activation, with >80% of Treg cells expressing the activation markers CD38, ICOS, and OX40." (PMID 36934113, 2023). "In contrast, ICOS monotherapy and ICOS/PD-1 combination group exhibited higher and more homogeneously-distributed CD8+ T-cell tumor infiltration as reflected by a higher IHC scoring in the core relative to the IgG controls." (PMID 36266600, 2023). "This study investigated the distribution of ICOS and ICOSL expression in different groups, including gender, age, smoking history, tumor size, regional node metastasis, different stages, recurrence, and survival." (PMID 37850501, 2023). "In addition, the induction of Tregs through the ICOS/ICOSL pathway could potentially create a vicious cycle by producing additional TGF-β that further intensifies the immunosuppressive effect of the tumor." (PMID 37669110, 2023). "In ovarian cancer, an 18-gene signature (including TAP1, ICOS, CD2 COL5A2) has been described to immunologically characterise desert tumours in coherence with histopathological analysis for intratumor T-cell levels." (PMID 37454231, 2023). "Strategies targeting Tregs to increase anti-tumor immunity, including antibodies against CTLA-4, OX40, 4-1BB, and ICOS, have attracted attention." (PMID 37729184, 2023). "Our data show that Vγ6+ cells express a phenotype with high degree of similarity to Trm CD8+ T cells through production of CXCR6, ICOS, JAML, and PD-1, whose expression is stable between tumor-free and tumor-bearing mice." (PMID 36480166, 2023). "In total, 72 genes were identified as significantly up-regulated, which include many genes (including OLR1, ICOS, and SERPINE1) that previous reports have demonstrated their correlation with tumor cell migration and metastasis." (PMID 37244923, 2023). "ICOS is expressed on a subset of CD4+ T cells, CD8+ cytotoxic T cells, and most regulatory T (Treg) cells in tumor-infiltrating lymphocytes (TIL), across several indications." (PMID 37593752, 2023). "Single agent anti-PD-1 or anti-CTLA-4 increased the infiltrating ICOS+ CD4+ T cells to a similar degree, but combination blockade interestingly had a greater effect on the percentage of tumor-infiltrating lymphocytes (TILs) composed of ICOS+ CD4+T cells." (PMID 37449205, 2023). "Inducible co-stimulator (ICOS) is expressed on immunosuppressive Treg cells and pDCs in the OC TME activate Treg cells by expressing the ICOS ligand, resulting in tumor progression." (PMID 37298230, 2023).
tumor (continued). "We also inspected the associations between immune signatures identified in TB with the clinical features and revealed a higher abundance of Tregs (C06), PD-1+ICOS+CD8+ TEM cells (C18), CD49a+ NK cells (C24) in tumor border for advanced HCC patients." (PMID 37353792, 2023). "Emerging literature reports that ICOS or ICOSL is dysregulated in various cancer types and contributes to tumor immune escape." (PMID 37850501, 2023). "High expression of ICOS was significant for both PFS (p = 0.040) and OS (p = 0.041), while high PD-L1 expression in tumour cells was significant for OS (p = 0.033)." (PMID 37527282, 2023). "In particular, tumor angiogenesis and metastasization and migration of ECs, DCs and tumor cells are promoted by OPN and inhibited by ICOS." (PMID 36769276, 2023). "Quantitative comparative analysis using mRNA expression data from TCGA database on LUAD demonstrated that there is a significant difference in the expression of ICOS and ICOSL between normal tissues and tumor tissues." (PMID 37850501, 2023). "Equivalently to feladilimab, alomfilimab (mAbID 1120) and vopratelimab (mAbID 801) activate and induce the proliferation of low ICOS+ Teff cells, enhancing CTL-mediated anti-tumor immune response." (PMID 37215135, 2023). "A second eigenprotein score was calculated, using the scaled abundance of CD3 and ICOS, to reflect the intraepithelial T-cell activation status (TCA score) of each tumor (Cox HR 0.63, 95% CI: 0.36, 1.08, p = 0.08)." (PMID 37072398, 2023). "We are able to show the presence of lymphocytes and immune checkpoint markers especially PD-L1, ICOS and IDO1 within tumour samples and their significance in terms of patient survival." (PMID 37527282, 2023). "The analyses of the co-expression of immunomodulatory molecules PD-1, PD-L1, ICOS, LAG3, TIM3, and IDO showed heterogeneous populations of immune and tumor cells." (PMID 38047086, 2023). "Analysis by multiplex IHC showed that ICOS and PD-1 are often coexpressed on CD3+ cells in the TME in different tumor types." (PMID 37593752, 2023). "The expression of PD-1, ICOS, and CCR7 on T cells in tumor tissues was significantly higher than that of T cells in paratumor tissues." (PMID 35725444, 2022). "On the other hand, expressions of both EV-derived ICOS and IDO1 displayed a high correlation with the content of circulating tumor marker CA72.4." (PMID 36077704, 2022). "ICOS/ICOSL and CD28/B7-1/B7-2 are T cell co-stimulators and CTLA-4 is an immune checkpoint inhibitor that play critical roles in the pathogenesis of neoplasia." (PMID 36618349, 2022). "These included genes consistent with pro-inflammatory immune responses (CD27, CD28, CD3e, CD8a, ICOS, ICOSLG, Pax5, TBX, GATA3, HLA-A, TNFSF14, GPR146), but also immune suppressive influences in the tumor immune microenvironment (CTLA-4, FoxP3, PD-1)." (PMID 36698398, 2022). "These phenomena reflected that ICOS and IDO1 expression in both plasma and tissue levels was reflective of unique tumor-microenvironmental features." (PMID 36077704, 2022). "To obtain enough Treg cells, we analyzed splenic Treg cells and found that UDCA also reduced the population of splenic Treg cells and their TGF-β1, CTLA4, ICOS, and GITR levels in tumor-bearing mice." (PMID 35701426, 2022). "The T cell receptor repertoire of the PD-1+ICOS+ CD4+ Th TILs was oligoclonal, with T cell clones expanded in the tumor, but present at low frequencies in the periphery." (PMID 35439168, 2022). "The ICOS/ICOSL (CD275/CD278) pathway regulates the Treg population and, subsequently, tumor development." (PMID 36160406, 2022). "A recent study using a 89Zr-labeled anti-ICOS antibody in a lung cancer model detected activated CD4+ and CD8+ T cells in the tumor and tumor-draining lymph nodes in response to a STING immune agonist treatment." (PMID 35223381, 2022).
tumor (continued). "Alongside TNFRSF4/OX40 and TNFRSF9/4-1BB, we selected a number of markers of tumor-resident Tregs (CTLA4, ICOS, TIGIT, and FOXP3) and performed k-means clustering for all UPS, MFS, and DDLS samples in the TCGA." (PMID 35558159, 2022). "We observed significantly higher levels of exhaustion (ICOS, TIM3, CTLA4, PD1, LAG3, TIGIT) and activation (TNFSR9, CD69, CD25) markers for clonotypes restricted to the tumor." (PMID 36185254, 2022). "After the use of combination immunotherapy, an increase in T helper type 1 cytokines, ICOS+Ki67+CD4+, and ICOS+Ki67+CD8+ T-cells was observed as well as an increased CD8+ Tcell/FoxP3+ Treg ratio within the tumor." (PMID 36010854, 2022). "While this activation marker returned to baseline on Day 14 for CD8+ and non‐regulatory CD4+ T cells, dual expression of ICOS+/PD1+ Tregs was reduced 0.73‐fold (p = 0.0474), which also indicates a more immunostimulatory tumor microenvironment." (PMID 36176603, 2022). "Then, we analyzed the correlation between SLC3A2 expression and 60 immune check-point genes, of which 24 were stimulatory, like ICOS and CD28, while the other 36 genes were inhibitory for anti-tumor immunity, such as PD1 and PDL1 (CD274)." (PMID 35992269, 2022). "In our tumor-bearing mice, the expression of ST2 and ICOS on ILC2s was significantly elevated in both the micro- and macrometastatic regions compared to normal lungs." (PMID 35805039, 2022). "Using this dataset, we performed differential gene expression analysis between each of the timepoints for both tumor and TDLN samples and specifically examined ICOS expression." (PMID 36056093, 2022). "Specifically, activated Treg cells destroy tumour immunity by enriching a series of costimulatory molecules (such as ICOS, CD27, 41BB, OX40, and GITR) and immune checkpoints (PD-1, CTLA-4, LAG3, and TIGIT) to promote tumour immune evasion." (PMID 36110969, 2022). "Collectively, these data draw a picture in which the triggering of ICOSL by one or other of the binding partners, ICOS and OPN, mediates opposing activities on tumor metastasis, which is promoted by OPN and inhibited by ICOS." (PMID 35052731, 2021). "It emerged that the three members of the ICOS/ICOSL/OPN network play distinct and differing roles, possibly acting both at the tumor cell level and at that of the TME." (PMID 35052731, 2021). "In naive/Tcm CD4 T cells, there was reduced expression of CD28, ICOS, and OX40 in tumor compared with normal, with little PD1 expression and reduced CTLA4 expression in tumor T cells." (PMID 34936871, 2021). "At the same time, TApDCs not only exhibit less production of IFN-α, mainly mediated through tumor-derived TNF-α and TGF-β, but also induce tumor infiltration of ICOS+ Foxp3+ Tregs and drive immunosuppression via ICOS/ICOSL stimulation." (PMID 34737750, 2021). "highlighted the importance of immune status in prognostication—PDL1 and B7-H4 on tumour cells and PDL1, B7-H3, B7-H4, IDO-1, VISTA, ICOS, and OX40 on intralesional immune cells." (PMID 34956172, 2021). "The results showed that 5 proteins (ADAM23, ARHGAP20, ICOS, IRF4,MMRN1) were significantly different in tumour tissues compared with normal tissues." (PMID 33949771, 2021). "We can speculate that low expression of ICOSL in the primary tumor might favor detachment of tumor cells, their survival in the blood stream, and their extravasation at the metastatic site, since these cells would be less sensitive to the dominant negative inhibition triggered by ICOS." (PMID 35052731, 2021). "Collectively, these data suggest that OPN produced by TME favors tumor metastasis by interacting with stromal ICOSL; these activities are dominantly inhibited by ICOS." (PMID 35052731, 2021). "The presence of some activating receptors such as OX40 and ICOS was increased in the surface of CD8 cells in the tumor, whereas the inhibitory receptor LAG3 was reduced in tumor-specific CD8+ T lymphocytes." (PMID 33920699, 2021).
tumor (continued). "Other co-stimulatory receptors include OX40, CD137 (4-1BB), CD27 and inducible T cell co-stimulator (ICOS) on T cells and CD40 on APCs or tumor cells." (PMID 34439292, 2021). "We described features shared between the tumour and the peripheral blood, especially the circulating TIGIT+ICOS+ Tregs." (PMID 33917832, 2021). "Novel therapies targeting inhibitory (e.g., IDO-1, LAG-3, TIGIT, TIM-3, VISTA) and stimulatory (e.g., ICOS, GITR, OX40, 4-IBB) proteins within the tumor microenvironment (TME) are under active investigation." (PMID 34093591, 2021). "Compared to C57BL/6, ICOSL-KO mice displayed more B16-ICOSL-high metastases and fewer B16-ICOSL-low metastases, which runs counter to the dominant negative effect exerted by ICOS on adhesion and migration of ICOSL-expressing tumor cells." (PMID 35052731, 2021). "Beside its effect on tumor cell migration and survival, the network also plays a role in tumor neoangiogenesis, since OPN induces—while ICOS inhibits—angiogenesis." (PMID 35052731, 2021). "Activated peripheral γδ T cells can either induce anti-tumor activity of NK cells through CD137L (4-1BBL) expression or mediate NK pro-inflammatory cytokine production and DC editing through CD278 (ICOS) co-stimulation." (PMID 32509594, 2020). "Resemblance with human AITL disease increased upon immune-phenotyping showing that the tumor mouse tissues (spleen, liver, lymph nodes) were marked by a specific increase of CD4+PD1+CXCR5+ICOS+CXCL-13+Bcl-6+ T follicular helper (Tfh) cells as compared to WT." (PMID 32796826, 2020). "Several markers significantly correlated with CD3 expression in the tumour compartment, including CD40, CD44, CD14, B2M, Tim-3, CD8, CD45RO, and ICOS, potentially implicating other cell lineages in immune-associated anti-tumour activity." (PMID 33261133, 2020). "As HCC patients have an increased prevalence of tumor-infiltrating ICOS+ Tregs and this subset is regarded as a potent immunosuppressor in HCC, these observations warrant further investigation of ICOS signaling inhibition." (PMID 33036244, 2020). "It is significantly higher in tumor tissues than in ANT and PBMC, expressing FOXP3, CD25, ICOS, and so on." (PMID 32659053, 2020). "The benefits of this immunotherapy are a result of ICOS-activated PI3K signaling and T-bet expression that drives IFN-γ secretion and changes the tumor suppressive immune microenvironment to a Th1 cell-dependent anti-tumor immune state." (PMID 32983168, 2020). "MEDI-570 is an IgG1κ mAb that attaches to the ligand-binding domain of ICOS expressed on tumor-infiltrating CD4 + T cells, therefore preventing the interaction between ICOS + T cells and plasmacytoid dendritic cells (pDCs)." (PMID 33384022, 2020). "Agonistic antibodies and/or RNA aptamers targeting receptors including 4-1BB, OX40, CD40, GITR, ICOS and CD28 are in pre-clinical development, and have shown anti-tumor activity in mouse models of cancer." (PMID 31959281, 2020). "Recent data demonstrated high expression levels of ICOS and its ligand B7H2 (ICOSL) in GIST, an intercellular interaction promoting the expansion of Tregs that correlated with a poor prognosis in these tumours." (PMID 33207697, 2020). "A previous report demonstrated that ipilimumab treatment increases expression of ICOS on conventional CD4+ T cells in both blood and tumor tissue in patients with bladder cancer." (PMID 31192215, 2019). "Co-targeting the inhibitory receptor LAG-3 or the activating receptor ICOS on the TAI cells further enhanced this subset and resulted in improved tumor immunity." (PMID 31412943, 2019). "Exhausted T cells also highly express costimulatory receptors, like ICOS, CD28, 4-1BB shown in this study, so ICB plus co-stimulation agonists targeting these costimulatory receptors are also actively explored in tumor immunotherapy." (PMID 31783783, 2019).